CD4 (CD4 molecule)
Diseases named in the same sentence as CD4 in open-access papers (continued):
Sharing a sentence is not in itself a finding about the gene and the disease.
tumor (continued). "Since clonal expansion of tumor antigen specific T cells induced by Ad-Flt3L-TK was inhibited by PC61 administration, we next determined whether PC61 affects the influx of CD4+ and CD8a+ T cells into the tumor, the draining lymph nodes and the spleen after treatment with Ad-Flt3L and Ad-TK." (PMID 18431473, 2008). "There was a significant increase in the number of CD8+ T cells present in the untreated right tumour when the left tumour was treated with PDT (P<0.01 5 days post-treatment as compared to SR), which was accompanied by a slight decrease in the number of CD4+ T cells." (PMID 17505510, 2007). "In addition, a humoral response may be involved, as antigen-presenting cells can take up secreted tumour-derived DKK1 and elicit a CD4+ helper T-lymphocyte response." (PMID 17245340, 2007). "Furthermore, our studies suggest that the control of distant EMT6 tumours is independent of CD4+ T cells, but dependent upon NK cells." (PMID 17505510, 2007). "In support of our hypothesis that Treg inhibit innate immune responses, we found that adoptive transfer of CD4+CD25+ cells but not CD4+CD25– cells inhibited tumour rejection in RAG–/– mice." (PMID 17294404, 2007). "We have previously reported a significant and sometimes striking enrichment in CD4+CD25+ T cells among tumour-infiltrating lymphocytes in patients with SCCHN, and thus we hypothesise that these cells may preferentially localise to tumour sites." (PMID 15714205, 2005). "Furthermore, it is possible that some factors, such as tumor-derived antigens or molecules, can induce apoptosis selectively in the CD4+CD25- subset but not in the CD4+CD25+ subset." (PMID 15679891, 2005). "However, they did not assess the tumour CD4+ T-lymphocyte infiltrate and used a less extensive sampling method." (PMID 15700032, 2005). "Thus, our results might suggest altered functions of CD4+ and CD8+ T-lymphocytes in the context of anti-tumor immunoreactivity." (PMID 15613231, 2004). "The pathway by which lymphocytes, or specific subpopulations of lymphocytes, trigger the expression of TP is not clear, although there are reports implicating CD4 positive cells in tumour angiogenesis and natural killer (NK) cells in complex interactions with angiogenic factors." (PMID 11986782, 2002). "Moreover, CD4 KO mice failed to produce substantial amounts of the tumour suppressive cytokine IFN-γ." (PMID 10496366, 1999). "Importantly, combining CD4+ and CD8+ T cells at a 1:1 ratio—whether iPSC-derived or primary—resulted in intermediate levels of tumor control, T cell proliferation, and cytokine production, without surpassing the performance of the CD4+ T cell alone." (PMID 41484912, 2026). "In addition, PMV/Ivm-NC secured pronounced tumor-growth inhibition, down-regulation of oncogenic markers (VEGF and cyclin D1), upregulation of pro-apoptotic Bax and caspase-3, and enhanced immune-infiltration of CD4+ and CD8+ T-cells, suggesting Ivm-induced immunogenic cell death." (PMID 41495333, 2026). "However, not all CD4+ T cells contribute to anti-tumor immunity." (PMID 40176817, 2025). "Importantly, the combination therapy enhanced CD4+ and CD8+ T-cell infiltration, increased the production of pro-inflammatory cytokines such as IL-2, and reduced the expression of immunosuppressive factors such as IL-6, indicating an immunomodulatory effect that improved anti-tumor immunity." (PMID 41041327, 2025). "Compared to the control and αPD-L1 groups, the SB and SB+αPD-L1 groups tended to have higher percentages of CD8+ T cells, despite not having more lymphocytes, CD3+ T cells, and CD4+ T cells, suggesting that SB plus αPD-L1 might boost the tumor immune microenvironment." (PMID 40458404, 2025). "In addition to the elevated CD4:CD8 T cell ratio in ME patients (p value < 0.05), ME tumours showed higher proportions of Treg, activated Treg, and gamma-delta (gd) T cells, while AE tumours had higher proportions of T follicular helper (fh), naïve CD4 cells and CD8 effector memory (EM) cells." (PMID 39915477, 2025).
tumor (continued). "Moreover, CD4+ T cells may also exert antitumor effects by assisting CD8+ T cells or, in some cases, directly recognizing antigens presented on the surface of tumor cells eventually followed by secretion of type 1 cytokines (TNF-α or IFN-γ) or direct cancer killing." (PMID 41029711, 2025). "CD68 expression has significant negative relation with tumor purity and significant positive correlation with tumor-infiltrating levels of CD8+ T cell, macrophage, myeloid dendritic cell and cancer associated fibroblast, has no relation with B cell, CD4+ T cell in PAAD." (PMID 40918116, 2025). "Macrophage–CD4+ T cell interactions may not always kill tumor cells." (PMID 40422244, 2025). "This is in contrast to tumor, where a much higher proportion of both cytotoxic and noncytotoxic CD4+ T cells globally expressed PD-1 and Tim-3 (which may be related to exhaustion), but lower levels of KLRG1, suggesting distinct mechanisms of regulation from blood." (PMID 40299576, 2025). "Moreover, CD4+ cytotoxic T lymphocytes (CTL) may exhibit tumor-suppressing effect independent of CD8+ T cells." (PMID 40248695, 2025). "Based on these findings, the tumor growth suppression observed in B16F10-mock tumors during CD4+ T cell depletion experiments may be primarily attributed to the removal of suppressive CD4+ T cells, including Foxp3+CD25+ Tregs, which may have enhanced CD8+ T cell-mediated anti-tumor immunity." (PMID 40243581, 2025). "Moreover, after HA@CD36i‐TR@siSCD1 treatment, we observed that in both LFD‐fed and HFD‐fed mice, the intratumoral CD8+/CD4+ T‐cell ratios increased significantly, with decreased Treg cells and increased TNF‐α and IFN‐γ levels, indicating that PCa transformed from a “cold” tumor to a “hot” tumor." (PMID 39736148, 2025). "Thus, we hypothesized that the CD4-derived tracer signal from tumor margins in nonresponding animals were due to increased accumulation of Treg cells, which suppress the therapeutic response and immune cell infiltration into the tumor." (PMID 40561008, 2025). "Notably, responder patients exhibited a pronounced increase in activated B cells, as well as naïve and central memory B and T cells, whereas non-responder patients uniquely display the presence of CD4 T regulatory cells, known to repress tumor-specific CD8 T cells cytotoxicity." (PMID 40287406, 2025). "Furthermore, negative correlation could be found between tumor cells and immune-associated cells such as CD8+ T cells, CD4+ T cells and plasma." (PMID 40963600, 2025). "Furthermore, the proportions of naïve T cells, CD4+ T cells, and CD8+ T cells in the peripheral blood were significantly higher in the treatment group compared to the negative control group, indicating that local immune cells in the tumor microenvironment primarily derive from the peripheral blood." (PMID 39979981, 2025). "CD4+ T cells not only provide assistance to CD8+ T cells in killing tumor cells, but also directly eliminate tumor cells that express MHC class II molecules, or exert indirect anti-tumor effects by secreting cytokines that could activate other immune cells, such as macrophages." (PMID 41394802, 2025). "Notably, RT plus Y332D markedly enhanced the infiltration of CXCR3+ T, CXCR3+ CD8+ T, CXCR3+ CD4+ T, and CXCR3+ NK cells versus either monotherapies or vehicle, potentially due to the recruitment of CXCR3‐positive lymphocytes into the tumor by CXCL10 secreted by tumor cells, which is promoted by RT." (PMID 40470716, 2025). "Furthermore, subcutaneous tumor model revealed that mp50 K144Q (equivalent to K146Q in humans) clearly restricted tumor growth and elevated the percentages of cytotoxic NK cells but not CD4+ or CD8+ T cells in tumors, indicating that the antitumor capacity of p50 K146ac relies on NK cell activation." (PMID 40289129, 2025).
tumor (continued). "Furthermore, we conducted an experiment in which we removed each of these three independent risk factors from the nomogram model, namely, model 1 without the MVI model 2 without the complete tumor capsule, and model 3 without CD4+ T cell density of the CT region." (PMID 41212769, 2025). "Moreover, in conformity with Xiong’s report, the proportion of Treg cells in activated CD4+ T cells was sharply reduced by sh-TBX21-transfected PCa cells, indicating that TBX21 might limit the anti-tumor property of CD8+ T cells via enhancing the proportion of Treg cells." (PMID 41573646, 2025). "Although CD4+ T cell infiltration was not significantly changed, TNBCvax vaccination enhanced Th1-associated cytokine production (IFNγ and TNFα) which is suggesting a functional shift in CD4+ T cell activity that supports overall immune activation and CD8+ T cell-mediated tumor control." (PMID 40969744, 2025). "In addition, CD4 T cells but not CD8 T cells expressed TdTomato in tumor-draining lymph nodes." (PMID 41331250, 2025). "Notably, Th1 CD4+ T cells were not detectable in this tumor type at the tested time point." (PMID 41210994, 2025). "Thus, the lack of tumor-cognate CD4+ T-cell responses may explain the limited anti-tumoral efficacy observed in vaccines restricted to epitopes stimulating CD8+T cells." (PMID 40573922, 2025). "Further studies indicated that when used as a first-line therapy in combination with chemotherapy and ICIs for non-squamous NSCLC, NEO-PV-01 could induce CD4+ T cells with effector and cytotoxic features, highlighting its potential in reshaping the tumor immune microenvironment." (PMID 40872921, 2025). "Moreover, tumor CD200R1 expression was strongly correlated (Spearman’s ρ > 0.5) with the expression of at least one of four commonly used T cell and myeloid infiltration markers (CD4, CD8A, CD11B and CD45) in tumors from multiple cancer types in The Cancer Genome Atlas (TCGA;)." (PMID 40428397, 2025). "Notably, genetic deletion of CD4+ T cells greatly promoted MC38 tumor growth and abolished tumor reduction conferred by RCOR2 KO in mice, supporting an inhibitory role of CD4+ T cells in RCOR2-induced tumor growth, either directly or indirectly through their regulation of other immune components." (PMID 40608411, 2025). "Moreover, there was evidence of increasing CD8 and CD4 T cells and NK cells within hepatic metastases after treatment, along with increased TLR and IFN signaling and Th1 T cell activation by gene expression analysis, suggesting tumor inflammation as a mechanism of response." (PMID 40665019, 2025). "Increased TGFβ activity may suppress the antitumor response through inhibiting CD4+ T helper cell function, decreasing the differentiation and function of cytotoxic T cells, promoting the pro-tumor TH17 response, and recruiting immune suppressive myeloid cells into the tumor microenvironment." (PMID 39858016, 2025). "Interestingly, there was a significant decrease in the frequency of CD4+ and CD8+ pre-effector cells, suggesting that cryoablation of primary tumor may be accelerating the development of effector/effector memory T cells in abscopal tumors compared to resection." (PMID 39703517, 2024). "Indeed, the DEN/CCl4 model demonstrates that, during the early stages of tumor development including liver injury and fibrosis, LSEC expression of immunoregulatory molecules increases, and this increase corresponds with the generation of exhausted hepatic CD8 and CD4 T cells." (PMID 39896805, 2024).
tumor (continued). "Indeed, when PDAC monocytes interact with tumour-specific CD4+ T cells they can acquire an anti-tumourigenic MHCIIHi phenotype, while in the absence of direct lymphocyte contact, tumour-infiltrated monocytes follow the default differentiation into FOLR2+ TAMs, promoting tumour growth." (PMID 39430099, 2024). "Considering the relatively constant proportion of CD4+ T cells within the T cell (CD3+) infiltrates in both NMSCs and NS, we asked whether the frequencies of CD4+ T cells that were Th1 and Th2 cells, and the Th1/Th2 ratio, of major relevance in tumor immunobiology were also maintained." (PMID 38891095, 2024). "Finally, comparative analysis between the spleen and tumor cells of mice treated with either CXCL10-Fc or control IgG showed that successful therapy led to a significant increase in CD4+ T cells and CD8+ T cells at the tumor site, but not spleen." (PMID 39474427, 2024). "We previously reported that CD4+ TICs was found to be a significant and independent prognostic factor for favorable OS and to correlate with longer TFI, implicating that CD4+ helper T cells may affect patient prognosis through involvement in tumor chemosensitivity." (PMID 39232704, 2024). "It is well-established that, unlike normal tissue cells, tumor cells produce a substantial amount of pro-inflammatory cytokines and chemokines, inducing chronic inflammation within the tumor microenvironment, thereby suppressing the activity and immune infiltration of CD4+/CD8+ T cells." (PMID 39845976, 2024). "In contrast, the majority of tetramer negative (Tetramer−) CD4+ T cells isolated from B16-3340 and B16-EV tumors, irrespective of SFB colonization, were regulatory-like T cells, expressing both T-bet and Foxp3, a phenotype associated with strong suppression of anti-tumor immune responses." (PMID 39185202, 2024). "This may reflect partial homing of effector T cells directly to the tumour tissue rather than the spleen, but may also reflect a blunted ability to proliferate compared to naïve CD4 T cells, which is consistent with previous comparisons of naïve vs effector T cell proliferation." (PMID 38125720, 2024). "Remarkably, CD4+ T cells, CD8+ T cells, neutrophils, dendritic cells, and natural killer (NK) cells were abundant in the FeFAM cluster A across nearly all the algorithms, suggesting that the immune cells within FeFAM cluster A may concurrently govern immune evasion and anti-tumor activities." (PMID 39076986, 2024). "In addition to the changes in TME, the analysis of tumor-draining lymph nodes revealed increased proportions of Ki67+ proliferative CD8+ and CD4+ T cells in Ptger4-KO tumor–bearing mice, suggesting that the disruption of tumor cell–intrinsic EP4 signaling may have systemic effects." (PMID 39298269, 2024). "Notably, these results also show that although CD4+ cells dominate the CD4+/CD8+ cell ratio in the blood and the tumor, the percentage of CD8+ T cells in the tumor increases, which indicates a potential expansion of these cells due to their engagement with the targeted tumor proteins." (PMID 39445067, 2024). "Despite these limitations, it is highly promising that an anticancer response in terms of an increase in the tumor-free survival and overall survival was noted in a mouse model lacking a conventional cell-based immune response (E6 and E7 not recognized as foreign and depletion of CD4 T cells)." (PMID 39339897, 2024). "Interestingly, although MHC-II expression did not statistically correlate with the total immune cell infiltrate in tumor islands (p=0.097), it strongly correlated with a high presence of both CD4+ TH (p=0.047) and CD8+ CTL (p=0.012), but not with CD68+ cells (p=0.099)." (PMID 39035008, 2024).
tumor (continued). "Notably, we identified EOCRC tumor-specific splicing of ZBTB7B (Th-POK), a zinc finger transcription factor which controls T-cell differentiation into CD4+ or CD8+ T-cells, and MAP3K8 (TPL2), a driver of oncogenic inflammation, though the biological function of these splice variants remains unknown." (PMID 38680862, 2024). "To explore whether the FAMRGs affect immune cell infiltration in tumor microenvironment, we conducted an analysis using the TIMER database to investigate the infiltration of 6 distinct immune cell types, including B cells, CD8+ T cells, CD4+ T cells, macrophages, neutrophils, and dendritic cells." (PMID 38923758, 2024). "Furthermore, the classification between the non-tumor and the tumor groups could be more correctly predicted by including information of Vpr and anti-Vpr IgG into age, CD4, CD8, HIV viremia, HBV, viremia, HCV viremia, IL-6, and TNFα." (PMID 38166062, 2024). "Additionally, GM-CSF improves the presentation of peptide antigens to CD4+ and CD8+ T cells, enhances the migration of DCs to lymphoid tissues, and stimulates the secretion of pro-inflammatory cytokines, thereby generating a robust and sustained anti-tumor immune response." (PMID 39204073, 2024). "In addition to direct cytotoxic activity, CD4+ T cells engineered with CD8-independent TCRs may secrete soluble factors and cytokines that provide antigen-specific help to enhance the activity and persistence of tumor-specific CD8+ T cells." (PMID 39287991, 2024). "Moreover, in clinically advanced patients, CD4+/CD8+ ratio and LMR decreased, while CD8+T cells levels increased, indicating that different immune cells within the CD8+T cells may play an inconsistent role at different stages of tumor progression." (PMID 38263363, 2024). "CD8+ and CD4+ T cells are well established as the most prominent mediators of anti-cancer immunity, so our results suggest that PIEZO1 may also have a molecular role that reflects cancer aggressiveness and the suppression of anti-tumor immunity in HR-negative breast cancer." (PMID 38398074, 2024). "Interestingly, in WT mice receiving EMT6 and Fab anti-CD200R, no tumor cells were detectable after immunotherapy (tumor cell vaccination), and the CD4+ cells produced increased TNFα/IL-2/IFNγ on stimulation with EMT6 in vitro, as had been seen already in CD200RKO mice." (PMID 38540350, 2024). "Consequently, DCs can process foreign NeoAgs through two distinct pathways: presentation via MHC II to CD4+ T cells, or translocation into the cytosol for entry into the MHC I processing pathway, which enables “cross-presentation” to CD8+ T cells that are specialized for tumor recognition." (PMID 38793749, 2024). "Chemokines and cytokines, such as IFN-γ, CXCL9, and CCL20, are related to the recruitment of CD4+ and CD8+ T cells, so the lack of chemokines and cytokines may lead to impaired recruitment of immune cells, thereby causing an immunosuppressive tumor microenvironment." (PMID 38982511, 2024). "However, articles that use animal models of liver tumors focus on the role of CD8 LTs, leaving a gap regarding the involvement of CD4+ T lymphocytes in tumor development/elimination, and do not consider the role of CD4+ T lymphocytes in homeostatic maintenance of the organ." (PMID 38690280, 2024). "Additionally, TIM-3(+) Foxp3 (+) CD4 T cells are preferentially distributed within the tumor nest rather than the peri-tumor matrix, which may contribute to the immunosuppressive tumor microenvironment." (PMID 39206199, 2024). "When examining total tumor mutational burden (indels and single nucleotide variants) continuously, we observed strong correlations with overall CD3+CD8+ T cells in both epithelial and stromal areas but not with epithelial or stromal area overall CD3+CD4+ T cells." (PMID 39763680, 2024).